PF4 (platelet factor 4)
Diseases named in the same sentence as PF4 in open-access papers (continued):
Sharing a sentence is not in itself a finding about the gene and the disease.
COVID-19 (continued). "In any case, the presence of platelet factor 4/heparin antibodies is clustered in patients with CSVT (after vaccination) compared with the pre-COVID-19 period, allowing conclusions about the pathophysiology of some but not all affected patients." (PMID 34609603, 2022). "There have been studies confirming the relationship between NAbs generation induced by COVID-19 vaccination and PF4, and we observed more abundant PF4 in the NAbs positive individuals." (PMID 36091008, 2022). "Platelet activation markers, such as P-selectin (a cell adhesion molecule) and platelet factor 4 (PF4), are highly increased in the plasma of COVID-19 patients, which supports the concept of enhanced platelet activation." (PMID 35284964, 2022). "The adenovirus antibodies were also notable for having significantly more affinity for PF4 (a major target of autoimmune coagulopathies in COVID-19) than SARS-CoV-2 antibodies." (PMID 36232795, 2022). "Recent studies have reported the potential role of PF4 in immune thrombosis in patients who received the COVID-19 vaccine." (PMID 35869501, 2022). "Positive PF4 can also be induced by adenoviral vector COVID-19 vaccine or RNA COVID-19 vaccine with low clinical relevance." (PMID 36091008, 2022). "Platelet factor 4 (PF4) and platelet-expressing chemokines pro-platelet basic protein (PPBP) were reported significantly downregulated in severe COVID-19 patients, which associated with platelet degranulation and potently contributed to thrombopenia." (PMID 35903092, 2022). "Antibodies against bacteria that are commonly found as co-infections in moderate-to-severe COVID-19, particularly Streptococci, Staphylococci, Klebsiella, and E. coli, also recognized multiple blood proteins, most notably CL, β2GPI, and PF4." (PMID 36232795, 2022). "The expression of cell-specific genes such as FCER1A in monocyte-derived dendritic cells, PPBP in megakaryocyte, ITGB3 in NK cells, and PF4 in T cells of COVID-19 patients was obviously lower than that in healthy controls." (PMID 36403042, 2022). "Recent studies have reported the potential role of PF4 in immune thrombosis in CVST patients who received the COVID-19 vaccine." (PMID 35869501, 2022). "The frequency of anti-PF4 was 5.6% and 8.0% after COVID-19 vaccination with Comirnaty (Pfizer/Biontech vaccine) and Vaxzevria (AstraZeneca), respectively." (PMID 36016324, 2022). "The prolonged up-regulation of PF4 after COVID-19 is therefore likely to contribute to a prothrombotic state." (PMID 36522333, 2022). "In a cohort of 222 COVID-19 patients with thrombosis, only nineteen (8.6%) tested positive for anti-PF4/heparin antibodies." (PMID 35371058, 2022). "Another notable result reported here is that none of the antibodies against any SARS-CoV-2 protein cross-reacted with CL which, like PF4, is a target of autoantibodies in most COVID-19 coagulopathies." (PMID 36232795, 2022). "Thrombo-inflammation can be induced by platelet activation, and PF4 levels upregulate significantly in COVID-19 patients and especially critically ill patients." (PMID 36091008, 2022). "In COVID-19 patients treated with unfractionated heparin, the formation of antibodies against the PF4-heparin complex has been reported." (PMID 33918932, 2021). "When compared to controls, the circulating levels of the platelet activation markers PF4 and sP-sel were significantly higher in COVID-19–positive individuals." (PMID 34360707, 2021). "Antibodies against PF4 were evaluated 22 days after the first dose of the vaccine, based on the known kinetics of adaptive immunity, both after COVID-19 natural infection and after vaccination." (PMID 34358129, 2021). "The model we support is based on the hyperactivation of platelets during COVID-19, which results in the release of PF4 into the circulation." (PMID 34443589, 2021).
COVID-19 (continued). "In such a scenario, both the adenovirus and the spike protein would contribute to the formation of immunogenic PF4 following vaccination with adenoviral vector-based COVID-19 vaccines." (PMID 34029337, 2021). "In such a scenario, both the adenoviral vector and the spike protein would contribute to the formation of immunogenic PF4 following vaccination with adenoviral vector-based COVID-19 vaccines." (PMID 34639132, 2021). "Autoantibodies to PF4 contribute to thrombotic thrombocytopenia, which occasionally occurs during COVID-19 or after vaccination with adenoviral vector-based vaccines against SARS-CoV-2." (PMID 34029337, 2021). "Circulating levels of platelet factor 4 (PF4) were substantially elevated in COVID-19 patients when compared to both hospitalised (HoC) and healthy controls (HeC) (p = 0.012 and p = 0.0033, respectively)." (PMID 33596198, 2021). "Consistently, we found that plasma PF4 levels were increased in COVID-19 patients, compared with healthy donors." (PMID 32887634, 2020). "Finally, we measured plasma-induced platelet-activation antibodies by PMA in all COVID-19 patients with positive anti-PF4/H results (patients #1, #2 and #3)." (PMID 40123654, 2025). "Intriguingly, vaccine-induced immune thrombotic thrombocytopenia (VITT), a rare but serious complication associated with adenoviral vector-based COVID-19 vaccines, also shares immunopathological features with CAC, namely, upregulated platelet activation via anti-platelet factor 4 (PF4) antibodies." (PMID 41303146, 2025). "It has been hypothesized that COVID-19 vaccination can activate autoimmune diseases through the production of autoantibodies (e.g., platelet factor 4 antibody-mediated platelet may lead to immune mediated thrombocytopenia)." (PMID 40142435, 2025). "Recently, HIT-like antibodies have been detected in VITT and COVID-19 patients using PF4/H ELISA, and therefore,we used PF4/H antibodies to understand if the SP also causes a change in PF4 conformation that facilitates the binding of HIT antibodies as heparin does." (PMID 38540666, 2024). "Moreover, fluorescence nanoscopy has been used to scrutinize the impact of epidemic disease vaccine, utilizing α-granules secretin, specifically platelet factor 4 (PF4), as a biomarker for efficacy of COVID-19 vaccines." (PMID 38910248, 2024). "More recently, antinuclear/extractable-nuclear antibodies and autoantibodies reacting with type I IFNs, Anti-Platelet Factor 4, were associated with COVID-19, although causation or correlation has not yet been established with the infection." (PMID 37656328, 2024). "Levels of P-selectin and anti-PF4 variables based on COVID-19 status." (PMID 39287233, 2024). "Platelets stimulated by endogenous heparin, either directly or with the intermediation of PF4, release additional heparin may lead to the catastrophic thrombotic thrombocytopenia observed in severe COVID-19 or following vaccination." (PMID 38034388, 2023). "Anti-PF4 antibodies may be involved in the pathophysiology of severe clinical complications of COVID-19." (PMID 36979908, 2023). "For example, several investigators have documented mimicry of PF4 for SARS-CoV-2 proteins so that it could be predicted that COVID-19 vaccines might induce autoantibodies that cross-react with PF4." (PMID 36769320, 2023). "However, recent studies have shown that anti-PF4 antibodies activate platelets and contribute to thrombosis in COVID-19, suggesting a different mechanism of platelet PF4 involved in SARS-CoV-2 infection." (PMID 37762435, 2023). "The main hypothesis for the pathophysiology of immune thrombotic thrombocytopenia induced by an adenoviral vector-based COVID-19 vaccine involves the reaction between cationic platelet factor 4 (PF4) and anionic-free DNA in the recombinant adenovirus vaccine." (PMID 37338722, 2023).
COVID-19 (continued). "The combination of PF4 and heparin to form antigenic complexes is an important mechanism in the pathogenesis of heparin-induced thrombocytopenia (HIT), but vaccine-induced immune thrombotic thrombocytopenia (VITT) related to the COVID-19 vaccine makes PF4 a research hotspot again." (PMID 36926331, 2023). "Of more modern interest, antibodies against PF4 may also arise in patients with COVID-19 or in patients who have been vaccinated against COVID-19, especially in recipients of adenovirus-based vaccines." (PMID 35225866, 2022). "Similarly, PF4 has been shown to interact with adenoviral vector derived from chimpanzee adenovirus Y25 (ChAdOx1) and its components used for vaccination against COVID-19." (PMID 35626650, 2022). "Notably, as mentioned in the Introduction, transient anti-PF4 antibodies have been demonstrated in 30 to 75% of adenovirus-vectored COVID-19 vaccinees, though autoimmune coagulopathies have remained extremely rare." (PMID 36232795, 2022). "However, the antibodies against platelet factor-4 (PF4) which are the hallmark of VITT, are only sporadically found in COVID-19 patients, and in most cases, they are functionally inactive." (PMID 36704480, 2022). "There are data suggesting that Ad26 and ChAdOx1 COVID-19 vaccines may induce this side effect by binding platelet factor 4 (PF4) and driving anti-PF4 antibody responses after leaking into the blood after IM injections." (PMID 36001674, 2022). "However, there is no specific mechanism for developing HZ after infection or vaccination with COVID-19 In AstraZeneca, the adenovirus used as a vector binds strongly to platelet factor 4 (PF4) and activates platelets." (PMID 36499742, 2022). "Moreover, anti-PF4 antibodies have been detected in those with severe COVID-19 as well as heparin-induced thrombocytopenia (HIT)." (PMID 36016187, 2022). "Outside of the COVID-19 and vaccination settings, a small percentage of aPL-positive individuals will have associated anti-PF4 antibodies that are non-platelet-activating." (PMID 36560433, 2022). "This may be related to the fact that the levels of circulating serotonin and platelet factor 4 (PF4) in the serum of patients with COVID-19 increase, which indicates degranulation of platelets." (PMID 36014561, 2022). "Also in COVID-19, several studies have shown a correlation between increase PF-4 levels and severe cases, as well as in cases of post-vaccine thrombosis." (PMID 36189282, 2022). "Furthermore, elevated levels of PF4 and platelet-neutrophil aggregates have been observed in COVID-19 patients." (PMID 35163743, 2022). "It will therefore be interesting for future studies to investigate whether autoantibodies to PF4 might contribute to post-COVID-19 thrombosis in some patients." (PMID 36522333, 2022). "PF4 expression is strongly elevated following trauma as well as in sepsis and COVID-19." (PMID 35874830, 2022). "Autoantibodies targeting PF4 have been implicated in the thrombosis and thrombocytopenia syndrome (TTS) induced in rare cases following vaccination with the ChAdOx1 nCoV-19 (AstraZeneca) or the Ad26.COV2.S (Johnson & Johnson) COVID-19 vaccines." (PMID 36303764, 2021). "Moreover, an increased secretion of platelet granular contents that is, PF4 (Platelet Factor 4) from alpha granules and 5-HT (serotonin) from dense granules was observed in COVID-19 patients, indicating the platelet activation." (PMID 33981235, 2021). "Platelet hyperactivity in COVID-19 can result from increased protein kinase C phosphorylation, the release of platelet extracellular vesicles, inflammatory cytokines PF4, TNF-α, IL-8, and IL-1β from platelets, inducing the formation of leukocyte-platelet aggregates." (PMID 34827548, 2021). "Strikingly, agonist-induced ADP release was 30- to 90-fold higher in COVID-19 patients compared with hospitalised controls and circulating levels of platelet factor 4 (PF4), soluble P-selectin (sP-selectin), and thrombopoietin (TPO) were also significantly elevated in COVID-19." (PMID 33596198, 2021).
COVID-19 (continued). "We found that hospitalized COVID-19 patients develop immunoglobulin Gs (IgGs) that recognize a complex consisting of platelet factor 4 and heparin similar to those developed in heparin-induced thrombocytopenia and thrombosis (HIT), however, independent of heparin exposure." (PMID 34013243, 2021). "However, further research into the formation of these anti-PF4 autoantibodies and the causes behind TTS following COVID-19 vaccination is required to identify potential interventions to prevent these events." (PMID 36303764, 2021). "The severe and critically severe COVID-19 patients presented the highest plasma PF4 levels." (PMID 32887634, 2020). "Notably, VITT-related anti-PF4 antibodies do not cross-react with viral spike proteins, and COVID-19-associated thrombosis operates distinctly from VITT pathways." (PMID 40733710, 2025). "Recently, platelet-activating spike/anti-spike and histone/anti-histone IgG complexes have been associated with some VITT cases that occurred after mRNA COVID-19 vaccination whose sera tested negative for anti-PF4 antibodies but were still able to induce FcγRIIA-mediated platelet activation." (PMID 40573981, 2025). "Moreover, platelet factor 4, orosomucoids 1 and 2, as well as platelet α-granule proteins: serglycin, platelet basic protein and thrombospondin 1 were all repressed in plasma six moths after COVID-19." (PMID 39183264, 2024). "They consequently coined the term, “pre-VITT syndrome,” indicating the critical period after vaccination with AV COVID-19 vaccines but preceding thrombotic complications where patients may present with severe headache, elevated D-dimer, and/or positive anti-PF4 IgG titer." (PMID 37261122, 2023). "Further, constituents of Ad-vector COVID-19 vaccines may play the role of “co-factor” binding to PF4, inducing newly formed immunogenic epitopes that potentially induce the production of the pathological anti-PF4 immunoglobulins." (PMID 38034388, 2023). "Likewise, it is unclear whether the formation of PF4 neoantigen complexes is a prerequisite to the pathogenesis of VITT after administration of a rAV-based COVID-19 vaccine." (PMID 38140254, 2023). "Similarly, ADAMTS13 levels were reduced (p = 0.009) and the VWF/ADAMTS13 ratio was increased (p = 0.0004) in convalescent COVID-19 patients with dysregulated angiogenesis and immunothrombosis, while levels of PF4 (a putative protector of VWF) were also elevated (p = 0.0001)." (PMID 36926331, 2023). "Interestingly, 4.3% of healthy blood donors have positive anti-PF4 antibody titers without previous therapeutic heparin exposure, suggesting that non-pathogenic anti-PF4 responses exist in some individuals (data collected prior to the COVID-19 pandemic)." (PMID 37261122, 2023). "More importantly, heparin-functionalized adsorbents could further exert beneficial effects by binding and depleting activated PF4 + platelets and PF4 + platelet extracellular vesicles, thereby contributing to the alleviation of immune thrombosis in sepsis and COVID-19 at multiple levels." (PMID 36855150, 2023). "Thus, COVID-19 coagulopathies are characterized by the presence of multiple autoantibodies besides anti-CL that include anti-β2GPI, anti-platelet factor 4 (PF4), anti-phosphatidylserine/prothrombin (aPS/PT), and anti-lupus coagulant (anti-La antigens), which are not usually present in MIS-C or KD." (PMID 36769320, 2023). "A major issue with the nebulizing administration route in severe COVID-19 is that there is concern that it will not reach the perialveolar vessels due to the high amounts of platelet factor 4 (PF4) that compacts NETs and decrease their susceptibility to DNase degradation." (PMID 35371025, 2022). "Moreover, anti-PF4 antibodies do not arise in the majority of COVID-19 patients and so cannot be considered a major driver of COVID-19-associated coagulopathy." (PMID 35225866, 2022).
COVID-19 (continued). "In summary, a small proportion of COVID-19 patients may have anti-PF4/X antibodies, only a fraction of which can be identified as anti-PF4/H antibodies, with the remainder representing antibodies against PF4, potentially in complex with an as yet unknown ‘anionic species’ (‘X’)." (PMID 35225866, 2022). "Regarding the mechanism by which immune thrombotic thrombocytopenia (ITT) is induced by an adenoviral vector-based COVID-19 vaccine, the main hypothesis relates to the reaction between the cationic PF4 and the anionic-free DNA contained in the recombinant adenovirus vaccine." (PMID 35455346, 2022). "Indeed, several studies report the presence of anti-PF4/heparin antibodies in COVID-19 patients." (PMID 34029337, 2021). "The circulating levels of the platelet activation markers PF4 and sP-selectin were highly elevated among our cohort of COVID-19–positive patients compared to controls which further supports the hypothesis that COVID-19 is associated with enhanced platelet activation." (PMID 33596198, 2021). "We also measured IgG anti-PF4/H levels in the sera from 61 patients with SID at baseline and after COVID-19 vaccination." (PMID 40123654, 2025). "However, in the context of CAC, this may also occur in the presence of heparin-binding proteins overexpressed in COVID-19, such as platelet factor 4, fibrinogen, and C-reactive protein, alongside the enzymatic degradation of heparin by heparanase and heparinase." (PMID 41303146, 2025). "Vaccine-Induced Immune Thrombotic Thrombocytopenia (VITT): Recently recognized as a rare complication of adenoviral vector-based COVID-19 vaccines, VITT is marked by the presence of high-titer anti-PF4 antibodies." (PMID 40276517, 2025). "All in all, our study highlights the distinct profiles of anti-PF4/H antibodies and platelet activation in HIT and VITT, demonstrating the irrelevance of systematically testing anti-PF4/H during COVID-19 or after vaccination in healthy subjects or in SID." (PMID 40123654, 2025). "Based on the known mechanism of HIT and our confirmation of binding between SP and PF4 as well as the presence of PF4- or HIT-like antibodies detected in VITT and COVID-19 patients, we propose a mechanism for the generation of these antibodies in patients." (PMID 38540666, 2024). "Incubation of platelets from COVID-19 patients with monocytes from healthy donors triggers the release of IL-1β, IL-6, IL-8, MIP-1α, MCP-1, TNF-α, PF4, and PDGF, and elevated levels of these factors were observed in clinical samples from COVID-19 patients." (PMID 38069209, 2023). "Elevated levels of PF4+ pEVs have been reported in sepsis, and there is evidence that HMGB1+ pEVs are significantly elevated in COVID-19." (PMID 35874830, 2022). "Similar to VITT in patients vaccinated by the AstraZeneca COVID-19 vaccine, CSVT and splanchnic veins thrombosis were also reported in individuals immunized by the J&J vaccine, corroborating the role of anti-PF4 synthesis in VITT." (PMID 35582622, 2022). "Since most COVID-19 coagulopathy patients display autoantibodies against vWF, PDE and PF4 along with CL, combinations of viral and bacterial infections appear to be necessary to initiate their autoimmune coagulopathies." (PMID 36232795, 2022). "The experts collectively emphasized that the presence of antibodies to platelet factor 4 is a key feature and driver of VITT with an adenovirus vector COVID-19 vaccine, which must be considered a specific newly identified syndrome." (PMID 36351906, 2022). "However, recent reports have found associations between COVID-19 patients and the development of heparin-induced thrombocytopenia (HIT), a condition associated with autoimmunity caused by platelet-activating anti-platelet factor 4 (PF4) antibodies forming an immune complex with heparin." (PMID 34930107, 2021). "In COVID-19 patients, platelet activation products, such as TXB2 and proteins from platelet α-granules PF4/CXCL4 and PDGF, are also released and found in tracheal aspirates." (PMID 34827548, 2021).